NPTN-IT1 (NPTN intronic transcript 1)
Synonyms: lncRNA-LET
Gene: Long non-coding RNA gene on chromosome 15 (73,567,012 to 73,569,294, reverse strand). Ensembl gene ENSG00000281183.
Diseases named in the same sentence as NPTN-IT1 in open-access papers:
NPTN-IT1 is named in the same sentence as 7 diseases in open-access papers, as found by Europe PMC text mining. Sharing a sentence is not in itself a finding about the gene and the disease. The quoted sentences say what the papers report.
breast carcinoma (1 paper, 2022). "In addition, we predict that nephronectin intronic transcript 1 (NPTN-IT1, also known as lncRNA-LET) may have relationship with breast cancer." (PMID 36744179, 2022).
cervical cancer (1 paper, 2023). A primary or metastatic malignant neoplasm involving the cervix. "NPTN-IT1 is a recently identified lncRNA, located on chromosome 15q24.1, which has a low expression level in tumor tissues and can inhibit the growth and metastasis of hepatocellular carcinoma, lung adenocarcinoma, nasopharyngeal carcinoma and cervical cancer." (PMID 37153000, 2023).
prostate carcinoma (1 paper, 2022). A carcinoma that arises from epithelial cells of the prostate gland. "So far, NPTN-IT1 and BOK-AS1 have not been found to be related to prostate cancer." (PMID 36360269, 2022).
NPTN-IT1 also shares sentences with these, for which no sentence is quoted: hepatocellular carcinoma (1 paper); lung adenocarcinoma (1); nasopharyngeal carcinoma (1); tumor (1).